LINC01644 (long independently transcribed non-coding RNA 1644)
Synonyms: LL22NC03-75H12.2
Gene: Long non-coding RNA gene on chromosome 22 (47,402,297 to 47,488,149, reverse strand). Ensembl gene ENSG00000218357.
Diseases named in the same sentence as LINC01644 in open-access papers:
LINC01644 is named in the same sentence as 1 disease in open-access papers, as found by Europe PMC text mining. Sharing a sentence is not in itself a finding about the gene and the disease. The quoted sentences say what the papers report.
gastric cancer (1 paper, 2021). A primary or metastatic malignant neoplasm involving the stomach. "The findings had to be verified using numerous experiment methods, and the molecular mechanism of LINC01697 and LINC01644 in progression and metastasis of gastric cancer will be further investigated." (PMID 34603561, 2021). "Compared to normal GES-1 cells, the relative mRNA expression levels of LINC01644 and LINC01697 significantly increased in gastric cancer cells, including SGC-7901, BGC-823, and HGC-27 (P < 0.05)." (PMID 34603561, 2021).